RN7SL560P (RNA, 7SL, cytoplasmic 560, pseudogene)
Gene: Miscellaneous RNA gene on chromosome 9 (128,709,780 to 128,710,043, forward strand). Ensembl gene ENSG00000264438.
Homologues: Orthologues: chimpanzee Metazoa_SRP (99% identical). Paralogues in human: RN7SL275P (76% identical), RN7SL376P (74% identical), RN7SL744P (73% identical), Metazoa_SRP (73% identical), RN7SL488P (69% identical), RN7SL48P (69% identical), RN7SL619P (69% identical), RN7SL377P (67% identical), RN7SL644P (66% identical), Metazoa_SRP (66% identical), RN7SL339P (64% identical), Metazoa_SRP (64% identical), and 704 more.